AIRE (autoimmune regulator)
Diseases named in the same sentence as AIRE in open-access papers (continued):
Sharing a sentence is not in itself a finding about the gene and the disease.
hypoparathyroidism (25 papers, 2010 to 2025). Hypoparathyroidism is an endocrine disorder in which the parathyroid glands in the neck do not produce enough parathyroid hormone (PTH). "APS I is a monogenic disorder that develops in childhood as a result of mutations in the autoimmune regulator (AIRE) gene and is a combination of Addison's disease (AD), mucocutaneous candidiasis, and hypoparathyroidism (hypoPT)." (PMID 39378147, 2025). "Autoimmune polyglandular syndrome type 1 (APS-1) is a rare inborn error of immunity caused by mutations in the AIRE gene, typically associated with chronic mucocutaneous candidiasis, hypoparathyroidism, and adrenal insufficiency." (PMID 40995360, 2025). "APS type 1 is characterized by a triad of Addison's disease, chronic mucocutaneous candidiasis, and hypoparathyroidism, due to mutations in the autoimmune regulatory gene, AIRE." (PMID 39607709, 2025). "Rarely, isolated hypoparathyroidism due to AIRE mutations has been documented, with decades of follow-up in which no other APS-1 features developed (exome-sequencing series and kindreds)." (PMID 41465179, 2025). "Isolated hypoparathyroidism is occasionally reported in individuals harbouring biallelic AIRE mutations, including in adult patients who have had long-term clinical follow-up." (PMID 35521792, 2022). "This revealed that >45% of probands with AIRE mutations had at least two diseases out of the triad of chronic mucocutaneous candidiasis, hypoparathyroidism, and adrenal insufficiency." (PMID 35521792, 2022). "AIRE mutations found in three isolated hypoparathyroidism patients have also been reported in our previous study." (PMID 34217342, 2021). "Autoimmune polyendocrinopathy-candidiasis-ectodermal dystrophy syndrome is a rare disease caused by biallelic mutations of the AIRE gene, usually presenting with the triad hypoparathyroidism-adrenal failure-chronic mucocutaneous candidiasis (CMC) and nonendocrine manifestations." (PMID 38605470, 2025). "Moreover, five probands with apparent isolated hypoparathyroidism, and who were referred for hypoparathyroidism gene panel analysis, were found to harbour homozygous AIRE mutations." (PMID 35521792, 2022). "Here, we describe the case of a preschool-age girl who presented with hypoparathyroidism, hepatitis, interstitial pneumonitis, and chronic polyarthritis at 4 years of age and was found to have two heterozygous disease-associated mutations in the AIRE gene." (PMID 28458664, 2017). "We describe the case of a preschool-age girl who presented with hypoparathyroidism, hepatitis, interstitial pneumonitis, and chronic polyarthritis at 4 years of age and was found to have two compound heterozygous disease-associated mutations in the AIRE gene." (PMID 28458664, 2017). "Notably, compound heterozygous mutations of AIRE can also cause isolated hypoparathyroidism." (PMID 34217342, 2021). "These are collectively referred to as “nonclassical APECED,” which differ from the classical form caused by biallelic deleterious AIRE mutations characterized by earlier onset CMC, hypoparathyroidism, or adrenal insufficiency." (PMID 41608501, 2025). "However, hypoparathyroidism as an early feature in all three affected family members (onset between 4 and 10 years) suggests a more pronounced and earlier onset autoimmune phenotype than commonly reported for monoallelic AIRE variants affecting the PHD1 domain." (PMID 41608501, 2025). "Type I PAS, caused by mutations in the AIRE gene, often includes POI as part of its clinical spectrum, alongside Addison’s disease, hypoparathyroidism." (PMID 40647723, 2025). "The juvenile type (APS-1) is caused by mutations in the autoimmune regulator (AIRE) gene on chromosome 21, and is defined by the combination of chronic mucocutaneous candidiasis, Addison’s disease, and hypoparathyroidism." (PMID 40041212, 2022). "Biallelic AIRE mutations were identified in 35 probands with APS-1 and 5 probands with isolated hypoparathyroidism." (PMID 35521792, 2022).
hypoparathyroidism (continued). "Mutations in the autoimmune regulator gen (AIRE), are responsible for APS-1 in which PAI is usually combined with hypoparathyroidism and mucocutaneus candidiasis." (PMID 32938577, 2021). "APS-1 is a very rare monogenic disorder caused by mutations in the autoimmune regulator (AIRE) gene and is characterized by the presence of two of the three main components: AD, chronic mucocutaneous candidiasis and hypoparathyroidism." (PMID 29089364, 2017). "Here, we describe a novel heterozygous AIRE variant, c.1010G>T (p.Cys337Phe), in three individuals from a Taiwanese-Singaporean family presenting with hypoparathyroidism, vitiligo, anemia, and ectodermal abnormalities, but not candidiasis." (PMID 41608501, 2025). "It is notable that around 30% of AIRE mutation-negative probands with suspected familial hypoparathyroidism harboured mutations in other genes known to cause hypoparathyroidism." (PMID 35521792, 2022). "Around 30% of AIRE mutation-negative probands with isolated hypoparathyroidism harboured mutations in other hypoparathyroid genes." (PMID 35521792, 2022). "Greater than 90% of AIRE mutation-negative probands with suspected familial hypoparathyroidism had apparently isolated hypoparathyroidism, and around 30% of these probands were found to have an abnormality affecting either the CASR, GATA3, GCM2, GNA11 genes or the 22q11.2 chromosomal region." (PMID 35521792, 2022). "Of concern, a substantial proportion of AIRE mono-allelic heterozygous mutations (4/12) in this group of Chinese patients were identified in the CARD and SAND domain, and only one case exhibited non-classical features (only hypoparathyroidism was found from the triad)." (PMID 34217342, 2021).
autoimmune polyendocrinopathy (21 papers, 2016 to 2025). A group of diverse conditions that are characterized by spontaneous, multi-organ autoimmunity, which target both endocrine (adrenal, gonad, pancreatic islet cells, parathyroid, pituitary, thyroid) and non-endocrine (gastrointestinal, integumentary, lymphatic) tissues. "Aire knockout mice (Aire−/−), which were developed to study the disease autoimmune polyendocrinopathy‐candidiasis‐ectodermal dystrophy that results from a mutation in AIRE, are prone to mild systemic autoimmune disease symptoms on the C57BL/6 background." (PMID 36069030, 2022). "PA is part of autoimmune polyglandular syndrome for which the underlying gene is autoimmune regulator (AIRE)." (PMID 33505716, 2021). "Reflecting its importance, AIRE deficiency is defined by the APS1/APECED syndrome for which autoimmune polyendocrinopathy and chronic mucocutaneous candidiasis are pathognomonic." (PMID 27426947, 2016). "One of these diseases is an inborn immune dysregulation syndrome called autoimmune polyendocrinopathy, candidiasis, and ectodermal dystrophy (APECED) resulting from mutations in the autoimmune regulator (AIRE)." (PMID 39292205, 2024). "Autoimmune polyendocrinopathy, candidiasis, ectodermal dystrophy (APECED) syndrome is a monogenic IEI caused by mutation of the autoimmune regulator (AIRE) gene." (PMID 36756122, 2023). "Autoimmune polyendocrinopathy with candidiasis and ectodermal dystrophy (APECED) is a rare disorder of immune dysregulation caused by mutations in the autoimmune regulator (AIRE) gene." (PMID 28458664, 2017). "Autoimmune regulator (AIRE) deficiency in humans induces a life-threatening generalized autoimmune disease called autoimmune polyendocrinopathy–candidiasis–ectodermal dystrophy (APECED), and no curative treatments are available." (PMID 35269691, 2022). "Dysfunction of the AIRE gene could lead to autoimmune polyendocrinopathy-candidiasis-ectodermal dystrophy." (PMID 30403260, 2018). "The first condition is the APECED (Autoimmune polyendocrinopathy, candidiasis and ectodermal dystrophy)/APS1 (autoimmune polyglandular type 1) syndrome, which is most frequently owing to loss of function mutations in both alleles of the AutoImmune REgulator (AIRE) gene." (PMID 40093006, 2025). "One patient was shown to have a heterozygous missense variant in AIRE (p.R471C), which has previously been published as being associated with autoimmune features but not overt APECED (autoimmune-polyendocrinopathy-candidiasis-ectodermal dystrophy)." (PMID 34390440, 2021).
chronic mucocutaneous candidiasis (21 papers, 2014 to 2025). "AIRE-deficiency leads to multiorgan system autoimmunity and susceptibility to chronic mucocutaneous candidiasis (CMC)." (PMID 33584685, 2020). "In this issue, the classical manifestations of APS1 were a triad of chronic mucocutaneous candidiasis (CMC), hypoparathyroidism, and adrenal insufficiency, but the clinical phenotype is expanding with improved detection of AIRE mutations." (PMID 33532929, 2021). "In addition, heterozygous dominant-negative AIRE mutations in the plant homeodomain 1 domain have also been described, associated with organ-specific APECED-associated autoimmune manifestations and/or chronic mucocutaneous candidiasis (CMC)." (PMID 28769929, 2017).
candidiasis (17 papers, 2016 to 2025). Infection with the organism Candida. "APS-1 is an autosomal recessive disease caused by mutation in the AIRE gene, presenting mainly in childhood with Addison’s disease, candidiasis, and hypothyroidism." (PMID 33716979, 2021). "Patients with autoimmune polyendocrinopathy candidiasis and ectodermal dystrophy (APECED)-syndrome bearing biallelic mutations in the autoimmune regulator (AIRE) gene are as well susceptible to Candida infections but no other pathogens." (PMID 26604104, 2016).
Addison’s disease (14 papers, 2010 to 2025). "AIRE mutations are well-established causes of monogenic Addison’s disease when it appears as a component in APS1, and thus explain a minor fraction of AAD cases." (PMID 29849176, 2018). "APS type 1 (ORPHA:3453), due to different mutations of the autoimmune regulator (AIRE) gene on chromosome 21, is characterized by the presence of chronic candidiasis, chronic hypoparathyroidism, and Addison’s disease." (PMID 37937054, 2023).
rheumatoid arthritis (11 papers, 2013 to 2025). A chronic, systemic autoimmune disorder characterized by inflammation in the synovial membranes and articular surfaces. "Several studies addressed the association of autoimmune regulator (AIRE) gene polymorphism with the risk of rheumatoid arthritis (RA); however, their conclusions were inconsistent." (PMID 29069728, 2017). "More recently, a polymorphism in AIRE has been found to be a determinant for predisposition to rheumatoid arthritis in the Japanese population." (PMID 25978041, 2015). "Recently, the AIRE gene was identified as a genetic risk factor for rheumatoid arthritis (RA) in genome wide association (GWA) studies performed in the Japanese population." (PMID 23320549, 2013). "Two SNPs in AIRE gene, rs2075876 and rs760426, showed strong association with rheumatoid arthritis risk suggesting that in addition to the key AIRE gene mutations and other genetic and environmental factors, SNPs may have an impact on the phenotypic expression of APECED." (PMID 37144156, 2023). "Genetic polymorphisms of AIRE have been associated with rheumatoid arthritis (RA), but no specific disease-mediating mechanism has been identified." (PMID 31275320, 2019).
Adrenal insufficiency (10 papers, 2018 to 2025). Insufficient production of steroid hormones (primarily cortisol) by the adrenal glands. "Originally characterized in the 1960s by scientists studying adrenal insufficiency, APECED is an autosomal recessive condition caused by LOF variants in AIRE, which encodes the transcription factor AIRE that is a core component of central T cell tolerance." (PMID 40842819, 2025).
Immunodeficiency (9 papers, 2015 to 2025). Failure of the immune system to protect the body adequately from infection, due to the absence or insufficiency of some component process or substance. "Various pathogenic mechanisms implicated in the development of immune dysfunction include decreased expression of the autoimmune regulator (AIRE) gene and the presence of anti-cytokine antibodies." (PMID 26649279, 2015). "The most frequently reported monogenic immunodeficiency disease that causes IC and CNSC is Caspase Recruitment Domain Family Member 9 (CARD9) defects, followed by Autoimmune Regulator (AIRE), Signal Transducer And Activator Of Transcription 1 (STAT1), STAT3, and Interleukin 17F (IL17F) defects." (PMID 36526986, 2022).
melanoma (8 papers, 2012 to 2026). A malignant, usually aggressive tumor composed of atypical, neoplastic melanocytes. "AIRE-deficient mice show reduced melanoma growth due to enhanced immune rejection and increased survival." (PMID 29795364, 2018). "AIRE is involved in susceptibility to melanoma perhaps regulating T cell immunity against melanoma antigens (MA)." (PMID 27563821, 2016). "Thirdly certain AIRE single nucleotide polymorphisms associated with reduced AIRE stability are significantly more frequent in healthy patients than in melanoma patients and so are Melan A-specific T cells, again implying protective effects of AIRE deficiency." (PMID 22506061, 2012). "On this basis, variations of AIRE gene activity, due to polymorphisms or gene alterations, could be related to protection or susceptibility to melanoma, as supported by several lines of evidence in humans and in animals." (PMID 27563821, 2016). "Hence, for the first time our data elucidate, at the genetic and molecular level, the processes linking the expression of a specific AIRE gene polymorphism to susceptibility to a neoplastic disease such as melanoma." (PMID 27563821, 2016). "In contrast to B16 melanomas, knocking down AIRE expression in DMG uncovered novel T cell targets for immune attack." (PMID 39606441, 2024). "AIRE deficiency finds to decrease the expression of Tyrosinase Related Protein 1 (TYRP1) in thymus, yet increases the T cell immune responses against melanoma development." (PMID 31641374, 2019). "Studies have shown that AIRE dampens the antitumor immune response in melanoma and sarcomas leading to cancer progression." (PMID 29795364, 2018). "Interestingly, APECED autoantibodies target cancer‐testis antigens, especially associated with melanoma, including members of the MAGE‐A, MAGE‐B, and GAGE families, and sperm‐specific proteins, suggesting a role for AIRE in antitumor immunity with potential implications for cancer immunotherapy." (PMID 41461613, 2026). "In addition, when the tumours had grown, the mice were approaching 12 months in age, by when their responsiveness may be declining, as we have noted to the melanoma B16F10 in AIRE−/− mice." (PMID 22506061, 2012). "Similarly, the enlarged T cell repertoire in AIRE−/− mice enables them to mount anti-MAA and anti-melanoma responses as shown by increased anti-melanoma antibodies, and enhanced CD4+ and MAA-specific CD8+ T cell responses after melanoma challenge." (PMID 22506061, 2012).
pernicious anemia (7 papers, 2010 to 2025). Megaloblastic anemia caused by vitamin B-12 deficiency due to impaired absorption. "The proband in our study presented with vitiligo and pernicious anemia, which have been previously linked to DN AIRE variants affecting the PHD1 domain." (PMID 41608501, 2025). "Pernicious anemia is commonly seen in other patients with PHD1 AIRE mutations." (PMID 37235056, 2023). "Patients harboring dominant-negative heterozygous mutations in AIRE, especially within the plant homeodomain 1 (PHD-1) domain, present with a milder phenotype and later onset with a propensity for pernicious anemia and vitiligo." (PMID 37235056, 2023).
type 1 diabetes (7 papers, 2010 to 2025). "The characterisation of Aire−/− models is a crucial step towards understanding the link of AIRE to autoimmunity as recent genome-wide association studies find AIRE as a risk gene for pernicious type I diabetes, autoimmune Addison's disease, and anemia, respectively." (PMID 36685668, 2023). "Patients with deleterious AIRE mutations develop Autoimmune Polyendocrinopathy-Candidiasis-Ectodermal Dystrophy (APECED) that presents with multiple pathologies, often including type 1 diabetes." (PMID 35464420, 2022). "Similar to Lupus, type 1 diabetes in mouse and humans is unified by T-cell tolerance regulators (CTLA4, IL2RA, CD226, AIRE, etc.)." (PMID 36090990, 2022).
autoimmune Addison's disease (6 papers, 2017 to 2025). "Recently, two protein-coding AIRE mutations, specifically rs74203920 and rs2075876, were linked to autoimmune Addison’s disease." (PMID 38673639, 2024).
Down syndrome (6 papers, 2020 to 2023). "Autoimmunity and deficiency of the transcription factor autoimmune regulator protein (AIRE) are known associations with Down Syndrome (DS)." (PMID 37205347, 2023). "Down syndrome is caused by the trisomy of chromosome 21 in which AIRE is located, and one study reported that AIRE messenger RNA levels were elevated in thymic tissue from patients with Down syndrome, although there are conflicting reports." (PMID 35313042, 2022). "These exons corresponded to 7 genes, 3 of which have been previously associated with Down syndrome: GART, DNMT3L and AIRE." (PMID 33081811, 2020).
vitiligo (6 papers, 2010 to 2025). Generalized well circumscribed patches of leukoderma that are generally distributed over symmetric body locations and is due to autoimmune destruction of melanocytes. "In addition to clinical associations with autoimmune thyroid diseases and vitiligo, there is a particularly high rate of AA in the rare recessive syndrome of type 1 autoimmune polyendocrinopathy (APS1), caused by mutation of the autoimmune regulator (AIRE) gene." (PMID 31277078, 2019). "Several candidate genes have been linked to vitiligo, such as genes involved in the leukocyte antigen system (HLA, MIM 615161), cytotoxic T lymphocyte-associated 4 (CTLA4, MIM 123890), tumor necrosis factors (TNFα, MIM 191160), and autoimmune regulators (AIRE gene, MIM 607358)." (PMID 25548428, 2014).
autoimmune hepatitis (5 papers, 2010 to 2025). Hepatitis caused by autoantibodies. "However, studies of known mutations in the AIRE gene in patients with autoimmune liver diseases have shown that mutations in this gene probably do not play a significant role in the pathogenesis of AIH." (PMID 36248826, 2022).
lupus (5 papers, 2015 to 2023). "Reinforcing this idea, SLE has rarely been described among Down syndrome patients, who demonstrate lower thymic expression of AIRE and are at high risk of developing organ-specific autoimmune diseases, but not lupus." (PMID 25999944, 2015).
alopecia (4 papers, 2010 to 2024). Hair loss usually from the scalp. "GO:0003712 (transcription cofactor activity), includes the gene AIRE, which is associated with alopecia." (PMID 28196072, 2017).
Arthritis (4 papers, 2017 to 2025). Inflammation of a joint. "In addition, there may be AIRE-independent genetic variants that enhance the risk of developing arthritis in APECED patients." (PMID 28458664, 2017). "Although further studies are required to fully understand the importance for AIRE in arthritis, our data supports a role for AIRE in peripheral effector cells in RA." (PMID 31275320, 2019).
COVID-19 (4 papers, 2021 to 2024). A disease caused by infection with severe acute respiratory syndrome coronavirus 2. "Both POU5F1 and AIRE genes have been mentioned in SARS133 literature-associated genes from Geneshot GeneRIF and also reported as up-regulated genes in COVID-19 infected bronchoalveolar lavage from patients and in COVID-19 patient’s whole blood (GSE166552)." (PMID 34407143, 2021).